TIGIT (T cell immunoreceptor with Ig and ITIM domains)
Diseases named in the same sentence as TIGIT in open-access papers (continued):
Sharing a sentence is not in itself a finding about the gene and the disease.
autoimmune disease (continued). "Our research, along with that of others in the field, demonstrates that TIGIT, similar to PD-1 and CTLA-4, could be another critically important molecule in effectively managing autoimmune diseases." (PMID 41597269, 2026). "The profile of TIGIT expression in lesions has been described in various malignancies and autoimmune diseases, but not in tuberculosis." (PMID 40526725, 2025). "CD226 and TIGIT are expressed at varying levels depending on the T cell subsets and activation states, and imbalance of the CD226/TIGIT signal is involved in the pathogenesis of cancer, autoimmune diseases, and inflammatory responses." (PMID 39349422, 2024). "The expression levels of TIGIT and CD226 depend on the T cell subset and activation level, and an increasing number of studies have demonstrated the importance of the TIGIT/CD226 axis in tumors and autoimmune diseases." (PMID 39349422, 2024). "Albeit data have shown that TIGIT functioned as an immune checkpoint in several autoimmune disorders, we did not observe T-cell activation and spontaneous autoimmune response in the gut of TIGIT−/− mice before the induction of colitis." (PMID 35844584, 2022). "Similar to PD-1, TIGIT, a novel immune checkpoint, which is mainly expressed on NKs, CD8+ T cells, CD4+ T cells, and Treg cells, is well known for its important role in tumor immunity and autoimmune diseases." (PMID 36426354, 2022).
pancreatic cancer (29 papers, 2019 to 2026). "The TIGIT-NECTIN2 axis was identified as an important immune checkpoint molecule in the tumor microenvironment of pancreatic cancer." (PMID 40855305, 2025). "A detailed analysis of human samples showed that pancreatic cancer has many TRM cells with a PD-1+TIGIT+ phenotype, and the promising potential of double blockade of PD-1 and TIGIT has been suggested." (PMID 39156900, 2024). "Another in vitro study in pancreatic cancer showed that dual blockade of PD-1 and TIGIT in TILs also rescued T cell effector function." (PMID 38335302, 2024). "In pancreatic cancer, high CD226 expression on CD8+ T cells is associated with response to PD1 and TIGIT blockade." (PMID 36717657, 2023). "Previous studies have demonstrated that TIGIT expression is elevated in various cancers, including pancreatic cancer 13, 41, bladder cancer 42, and cervical cancer." (PMID 37649613, 2023). "Previous studies have shown that pancreatic cancer has high-affinity MHC class I-restricted neo-epitopes, and the CD155/TIGIT signal axis is sufficient to facilitate immune evasion mediated by pancreatic cancer expressing neo-epitopes." (PMID 35433470, 2022). "The present study suggests that targeting the PD-1 and TIGIT signaling pathways enhances the response to neoantigen vaccines in pancreatic cancer, highlighting the potential synergy of these therapies in pancreatic cancer." (PMID 36569934, 2022). "The CyTOF analysis highlighted senescent T-cells and TIGIT+ICOS+ Tregs as potentially important immune cells in pancreatic cancer." (PMID 33917832, 2021). "It was observed that while TIGIT expression was similar between pancreatic cancer patients to that of healthy controls, CD155 was upregulated in pancreatic cancer tissue." (PMID 33946954, 2021). "There seems to be a dysregulation of the TIGIT/CD96/CD226/CD155 pathway involving NK cells in pancreatic cancer patients, warranting further in vitro and in vivo evaluation." (PMID 32117298, 2020). "Additionally, among the previous study, the role of TIGIT in pancreatic cancer and hematological malignancies has been related to anti-inflammatory and exhausted phenotypes as a consequence of tumor progression and negative patient outcomes." (PMID 40483533, 2025). "Our study showed that NECTIN2 is another important ligand of TIGIT in pancreatic cancer." (PMID 40855305, 2025). "These outcomes could partly explain chemotherapy with checkpoint inhibitory drugs such as PD-1/PD-L1 inhibitors showing modest benefit in clinical trials, and TIGIT inhibitors may be more proper as alternative immunotherapy for pancreatic cancer." (PMID 37173915, 2023). "We hypothesized that dual blockade of PD-1 and TIGIT synergizes with neoantigen vaccination in generating optimal anti-tumor immune responses in the KPC4580P pancreatic cancer model." (PMID 36569934, 2022). "To extend these findings, we investigated whether TIGIT signaling is an important immune regulatory pathway in human pancreatic cancer." (PMID 36569934, 2022). "Additionally, recent studies demonstrated that the CD155/TIGIT axis is a key driver of immune evasion in pancreas cancer, and that both PD-1 and TIGIT signaling impairs CD226 co-stimulation which is required for restoring antitumor immunity." (PMID 36569934, 2022). "However, TIGIT expression was found to be similar between pancreatic cancer patients and healthy controls, while CD226 and CD96 were downregulated." (PMID 32117298, 2020). "To test whether TIGIT signaling blockade can reinvigorate T cell responses in patients with pancreatic cancer, we added anti-TIGIT Ab to in vitro T cell cultures using PBMCs from a pancreatic cancer patient treated with a polyepitope neoantigen DNA vaccine on an expanded access protocol." (PMID 36569934, 2022). "In patients with pancreatic cancer, high TIGIT expression on CD8+ TILs at the gene and protein level corresponded to high cell‐surface TIGIT expression on peripheral CD8+ T cells." (PMID 39162097, 2024).
pancreatic cancer (continued). "In the pancreatic cancer microenvironment, NK cells down-regulate the activating receptor molecule CD226 and induce the increased expression of TIGIT." (PMID 35433470, 2022). "Based on single-cell sequencing analysis, the immune microenvironment of pancreatic cancer is characterized by the presence of a large number of immunosuppressive cell populations and functionally exhausted CD8+ T cells that express TIGIT." (PMID 35433470, 2022). "To predict the pancreatic cancer patients’ response to immunotherapy, we further investigated the difference in the expression of immune checkpoints (PD-1, PD-L1, CTLA-4, LAG3, TIGIT and TIM-3) between patients with low and high m6Ascore." (PMID 34332578, 2021). "In addition, chemotherapy reduces inhibitory checkpoint molecules in pancreatic cancer including CD80/CD86-CTLA4, LGALS9-HAVCR2, DPCD1LG2-PDCD1, and TIGIT-PVR." (PMID 37173915, 2023). "Supporting a role for CD226 and CD96 in the context of tumour evasion, a study of patients with pancreatic cancer demonstrated that CD226+CD96+ NK cells are deficient in patients versus healthy controls, while TIGIT was not altered." (PMID 30908480, 2019). "For example, recent studies reported that TIGIT promotes immune evasion by inhibiting the activation and function of NK and T cells, thereby contributing to disease progression and immune escape in cancers such as myelodysplastic syndrome (MDS) and pancreatic cancer." (PMID 40739089, 2025).
ovarian cancer (27 papers, 2020 to 2026). A primary or metastatic malignant neoplasm involving the ovary. "Collectively, these data indicate that in PB- and MA-derived macrophages from high-grade ovarian cancer patients the increased frequency of TIGIT, CD226, TIM-3, and LAG-3 positive cells is associated with an M2 phenotype." (PMID 37876933, 2023). "Treatment with a TIGIT inhibitor caused reduced tumor growth and improved NK cell functionality, both in mouse models of ovarian cancer and patient-derived cell cultures." (PMID 35327475, 2022). "Furthermore, the expression of CD163 and TIGIT was associated with unfavorable clinical parameters, indicating a prognostic relevance of M2 infiltration in ovarian cancer." (PMID 37876933, 2023). "In an ovarian cancer (OC) mouse model, TIGIT function was blocked using Anti-TIGIT monoclonal antibodies." (PMID 41596586, 2026). "For instance, dual blockade of TIGIT and LAG-3 in ovarian cancer models overcame compensatory checkpoint upregulation, while a tri-specific PD-L1/TIGIT/LAG-3 antibody outperformed benchmark therapies in T-cell expansion and tumor suppression." (PMID 40567374, 2025). "Findings indicate that NK cells derived from patients with advanced ovarian cancer typically exhibit a markedly immunosuppressive phenotype, whereas targeted TIGIT blockade specifically enhances the effector functions of the CD56dim NK cell subset." (PMID 40463500, 2025). "In tumor tissues and peripheral blood of patients, we further verified that FOXP4-AS1 played a m6A dependent role in ovarian cancer and TIGIT was abnormally elevated in the tumor microenvironment of patients with ovarian cancer." (PMID 37505151, 2023). "In a recent study, it was observed that the TIGIT blockade restored NK cell functionality on ovarian cancer patients who displayed altered expression of CD226, TIGIT, and CD96." (PMID 36231109, 2022). "We recently showed an upregulation of TIGIT on primary human NK cells after co-culture with ovarian cancer lines." (PMID 34452316, 2021). "TIGIT blockade boosts in vitro functional responsiveness of ovarian cancer ascites-derived CD56dim NK cells in patients with baseline reactivity against ovarian cancer tumor cells." (PMID 34367161, 2021). "Two clinical trials treating cancer patients including patients with ovarian cancer with TIGIT inhibitors in combination with other immunotherapies have recently been initiated, however, no results have been reported yet." (PMID 33352957, 2020). "The RNAseq data from the UKE ovarian cancer patient cohort showed that the expression of CD163 was correlated with other M2 markers, such as CD206 and CD204, and was also positively associated with the expression of TIGIT and TIM-3." (PMID 37876933, 2023). "Thus, we detected TIGIT expression in activated T lymphocytes from healthy subjects and ovarian cancer patients." (PMID 37359558, 2023). "Taken together, the blockade of TIGIT induced a phenotypic repolarization defined by a reduction of M2-associated receptors and ultimately resulted in a significant augmentation of the anti-CD47-mediated ovarian cancer phagocytosis." (PMID 37876933, 2023). "Our results are also in line with data from solid cancer, where blockade of TIGIT could boost functional responsiveness of NK cell subsets against ovarian cancer cell lines." (PMID 34884723, 2021). "However, checkpoint inhibitor treatment targeting PD1 and CTLA4 has been tested in ovarian cancer patients with sparse response rates, leaving TIGIT as a remaining potential target for treating HGSC recurrence." (PMID 33352957, 2020). "Together, these results indicate that NK cells act to increase the activity of oncolytic adenovirus in ovarian cancer and suggest that strategies to augment NK activity further via the blockade of inhibitory NK receptor TIGIT could enhance therapeutic potential of OVs." (PMID 32195317, 2020).
ovarian cancer (continued). "For advanced ovarian cancer, researchers have thoroughly investigated the regulatory mechanisms of the DNAM-1/TIGIT/CD96 signaling axis in NK cell-mediated antitumor immune responses." (PMID 40463500, 2025). "CD155, also referred to as the poliovirus receptor, functions as a shared ligand for both activating (DNAM-1) and inhibitory receptors (TIGIT, CD96), with its expression significantly upregulated across multiple tumor types, including ovarian cancer." (PMID 41567203, 2025). "Vδ1 T cells isolated of PBMC from healthy donors or ovarian cancer patients are mainly naïve, CM, TEMRA T cells, which highly expressed immune check point inhibitors and exhaustion markers such as TIGIT and PD-1." (PMID 38259448, 2023). "After incorporating the H-/L- expression groups of ICOS, TIGIT, CD8A, and TNFRSF8, the researchers categorized the ovarian cancer samples into 4 groups." (PMID 36157232, 2022). "By integrating the expression levels of ICOS, TIGIT, TNFRSF8, and CD8A, ovarian cancer patients can be divided into 4 subgroups, which have different prognosis." (PMID 36157232, 2022). "Our demonstration that blockade of the paired NK inhibitory receptor TIGIT further augmented NK cytotoxicity against OV-infected cells suggests that the combination of oncolytic adenovirus and TIGIT blockade may be a viable treatment strategy in ovarian cancer." (PMID 32195317, 2020). "Although recombinant human IL-15 (rhIL-15) can up-regulate the expression of DNAM-1 and TIGIT in a dose-dependent manner, DNAM-1 expression is significantly reduced during coculture of NK cells with ovarian cancer cell line spheroids or patient-derived tumor cells." (PMID 40463500, 2025). "Moreover, combined blockade of TIGIT and CD47 significantly increased phagocytosis of ovarian cancer cells by TAMs in comparison to a single blockade of CD47." (PMID 37876933, 2023). "Finally, the expression levels of ICOS, TIGIT, TNFRSF8, and CD8A were integrated for the purpose of grouping ovarian cancer samples by prognosis." (PMID 36157232, 2022). "We next observed that SPP1 expression was positively related with immune-checkpoint, such as CD274, CTLA-4, LAG3 and TIGIT, suggesting that SPP1 may play an important role in immune tolerance of ovarian cancer." (PMID 36585688, 2022). "Immune‐checkpoint molecules PD‐1, LAG3, CTLA4, TIGIT, and HAVCR2 (TIM‐3) have been identified and studied in various cancers including liver hepatocellular carcinoma, lung adenocarcinoma, stomach adenocarcinoma, ovarian cancer, and peritoneal carcinoma." (PMID 35184420, 2022). "In addition, TIGIT blockade was previously shown to prevent NK cell exhaustion and promote NK-dependent anti-tumoural responses in murine models, whilst we showed that TIGIT blockade could augment the NK cytotoxicity of oncolytic adenovirus-infected human ovarian cancer cells." (PMID 34452316, 2021). "We found that DNAM-1 expression was decreased and TIGIT expression increased on NK cells following co-culture with ovarian cancer cells, independent of virus infection." (PMID 32195317, 2020). "Considering the latest report in the field of tumor immunology, the TIGIT/CD155/DNAM-1 pathway plays the predominant role in OC progression and interactions of its components with the programmed cell death pathway create strong immunosuppression in the ovarian cancer TME." (PMID 36497240, 2022). "Thus, rather than targeting PD-1 alone, co-inhibition of TIGIT and PD-1 may represent a more effective strategy to restore NK cell function and surmount tumor immune escape in ovarian cancer." (PMID 41567203, 2025).
leukemia (25 papers, 2019 to 2026). A malignant (clonal) hematologic disorder, involving hematopoietic stem cells and characterized by the presence of primitive or atypical myeloid or lymphoid cells in the bone marrow and the blood. "The data indicate that circulating higher frequency of CD103+CD8+ T cells with lower expression of PD-1 and TIGIT are associated with favorable outcomes in patients with leukemia." (PMID 39391310, 2024). "Another recent study demonstrated that leukemia-associated macrophages express TIGIT and that blocking TIGIT drives M1-like phenotypes and increases phagocytosis." (PMID 37928556, 2023). "TIGIT expression is closely associated with PD-1 on T cells in patients with solid tumors or leukemia." (PMID 37670328, 2023). "In addition, we observed greater expression of PD-1 and TIGIT on T-cells from CLL patients with NFKBIE-mutated leukemia, further suggesting that NFKBIE mutations in CLL cells can promote T-cell exhaustion and contribute to escape from immune surveillance." (PMID 38486128, 2024). "Furthermore, high PD-1 and TIGIT expression are closely associated with late leukemia relapse after CAR-T therapy." (PMID 37291608, 2023). "A20 deletion resulted in even further reduction in Vav-cre Tet2fl/flTp53fl/fl leukemia burden and myeloid bias when coadministered with anti-TIGIT antibody." (PMID 40111422, 2025). "Laboratory studies have shown that blockade of the TIGIT signaling pathway can enhance NK cell-mediated anti-leukemia effects." (PMID 40463500, 2025). "In summary, elevated PD-1 and TIGIT expression levels in CD103+ T cells were observed in patients with leukemia in the DN and RR states." (PMID 39391310, 2024). "A small group of patients who had more TIGIT+ CD3+ T cells at the CR stage than those who relapsed had inferior survival, suggesting a potential contribution of exhausted T cells through TIGIT expression to leukemia relapse." (PMID 39684749, 2024). "TIGIT is an alternative checkpoint receptor (CR) whose inhibition promotes Graft-versus-Leukemia effects of NK cells." (PMID 38967649, 2024). "IBI939 is the first anti-TIGIT mAb approved for clinical use in China, and it is currently in Phase I trials for patients with leukemia and solid tumors." (PMID 37670328, 2023). "Other ICIs, such as TIM-3 and TIGIT inhibitors, have been extensively evaluated in clinical trials as treatments for different solid tumors and leukemia." (PMID 37670328, 2023). "In this review, we describe the gene and protein characteristics, biological functions, and abnormal expression profiles of LAG-3, TIM-3, and TIGIT in solid tumors and leukemia." (PMID 37670328, 2023). "More than 45 types of TIGIT inhibitors have been developed, and most of them are used in clinical practice for solid tumors and leukemia; however, only a few anti-TIGIT mAbs have been entered into Phase III clinical trials." (PMID 37670328, 2023). "IBI939 is the first anti-TIGIT mAb approved for clinical trials for leukemia and solid tumor therapy in China." (PMID 37670328, 2023). "Numerous preclinical studies have evaluated TIGIT blockade immunotherapy in the contexts of various solid tumors and leukemia." (PMID 37670328, 2023). "Moreover, the increased expression of TIGIT on CD8+ T cells has been related to poor prognosis during leukemia relapse after allo-HSCT and in advanced GC patients." (PMID 37670328, 2023). "The increased expression of PD-1 and TIGIT on these two subsets may attenuate their anti-leukemia function." (PMID 36742315, 2023). "Also, anti-TIGIT blockades can enhance NK cells’ cytotoxicity towards AML cells and repolarize M2 leukemia-associated macrophages into M1 phenotype and restore their phagocytic capabilities." (PMID 37291608, 2023). "Besides, blockage of TIGIT significantly increased IFNγ production and NK cell degranulation, contributing to NK cells mediated anti-leukemia effects." (PMID 36605439, 2022).